PRPF6 (pre-mRNA processing factor 6)
Diseases named in the same sentence as PRPF6 in open-access papers:
PRPF6 is named in the same sentence as 38 diseases in open-access papers, as found by Europe PMC text mining. Sharing a sentence is not in itself a finding about the gene and the disease. The quoted sentences say what the papers report.
retinitis pigmentosa (8 papers, 2012 to 2025). Retinitis pigmentosa (RP) is an inherited retinal dystrophy leading to progressive loss of the photoreceptors and retinal pigment epithelium and resulting in blindness usually after several decades. "Mutations in six spliceosomal proteins, PRPF3, PRPF4, PRPF6, PRPF8, PRPF31 and SNRNP200, cause retinitis pigmentosa (RP), a disease characterized by progressive photoreceptor degeneration." (PMID 25383878, 2014). "CDHR1, TTLL5, PRPF6, and IFT140 have been reported to play roles in human disorders of cone-rod dystrophy and cone dystrophy or retinitis pigmentosa." (PMID 35456484, 2022).
colon cancer (6 papers, 2020 to 2023). "PRPF6 in 20q13.33 is involved in androgen binding and has been shown to promote colon tumour growth via preferential splicing of genes involved in proliferation." (PMID 37079368, 2023). "ZAK-LF levels correlated with PRPF6 expression in colon cancer cells, and PRPF6 was required for the alternative splicing of ZAK to produce ZAK-LF." (PMID 33584830, 2021). "From this study, it was suggested that overexpression of PRPF6 has an important role in driving colon cancer, via the altered splicing of gene isoforms related to growth and proliferation." (PMID 33584830, 2021). "PRPF6 has been demonstrated to alter the constitutive and alternative splicing of a discrete number of genes in colon cancer." (PMID 33390843, 2021). "Expression of ZAK-LF transformed immortalised murine fibroblasts and induced xenograft tumour formation in immunodeficient mice, while depletion of ZAK-LF reduced the growth of PRPF6-overexpressing colon cancer cells in vitro and in xenografts." (PMID 33584830, 2021). "PRPF6 is reported to be related with spliceosome in colon cancer and androgen receptor (AR) signaling in hepatocellular carcinoma (HCC)." (PMID 33584809, 2020). "A recent study has validated that variation in PRPF6 may result in assembly and the corresponding function dysregulation of colon cancer cell spliceosome, which may lead to cancer." (PMID 32351780, 2020). "In colon cancer, PRPF6 (Pre-mRNA processing factor 6), a member of the tri-snRNP (small nuclear ribonucleic particle) spliceosomal complex, was shown to drive cancer cell proliferation by the preferential splicing of genes associated with growth regulation, making it a plausible target." (PMID 36833239, 2023).
autosomal dominant retinitis pigmentosa (5 papers, 2012 to 2026). Autosomal dominant retinitis pigmentosa (RP) is an autosomally dominant inherited retinal dystrophy leading to progressive loss of the photoreceptors and retinal pigment epithelium and resulting in blindness usually after several decades. "Mutations in PRPF6 and other pre-mRNA splicing factors have been reported to cause rare forms of autosomal-dominant retinitis pigmentosa." (PMID 22235333, 2012). "Pre-mRNA processing factors (PRPF6, PRPF8, and PRPF31) mutated in autosomal dominant retinitis pigmentosa and were identified as regulators during ciliogenesis." (PMID 36759599, 2023). "At least six different proteins of the spliceosome, including PRPF3, PRPF4, PRPF6, PRPF8, PRPF31, and SNRNP200, are mutated in autosomal dominant retinitis pigmentosa (adRP)." (PMID 30967900, 2019). "As an important member, PRPF6 mutation resulting in autosomal dominant retinitis pigmentosa (adRP) is not common." (PMID 36012314, 2022).
lung adenocarcinoma (4 papers, 2013 to 2023). A carcinoma that arises from the lung and is characterized by the presence of malignant glandular epithelial cells. "Of the 144 LTL genetic instruments, 12 colocalised with lung adenocarcinoma risk and revealed novel susceptibility loci, including MPHOSPH6, PRPF6, and POLI." (PMID 37079368, 2023). "Collectively, H2S impedes ATTM-induced anticancer effects through YTHDF1-dependent PRPF6 m6A methylation in lung adenocarcinoma cells." (PMID 32195181, 2020). "For example, a chromosome 20q cluster comprising four genes (PTK6, SRMS, RTEL1, and PRPF6) were all amplified in uterine/endometrial cancers and lung adenocarcinomas." (PMID 24874471, 2014). "In the present study, ATTM was found to promote cell growth, proliferation and invasion in lung adenocarcinoma cells, through YTHDF1-dependent PRPF6 m6A methylation." (PMID 32195181, 2020). "These genes include SMARCC1, TRA2B, CBX3 and PRPF6 that show the same upregulation pattern as EGFR in lung adenocarcinoma and we have reported all the mentioned genes for the first time in lung adenocarcinoma." (PMID 23874428, 2013).
lung carcinoma (4 papers, 2017 to 2024). "Actually, PRPF6 has been reported to promote lung cancer growth." (PMID 32195181, 2020). "Overall, our study identified six SNPs within mRNA splicing-related gene PRPF6 that might play an important role in the development of lung cancer." (PMID 28304396, 2017). "Several colocalised loci mapped to genes that have not been previously linked to lung cancer risk at genome-wide significant level: MPHOSPH6 (16q23.3; rs2303262), PRPF6 (20q13.33; rs80150989), and POLI (18q21.2; rs2276182)." (PMID 37079368, 2023).
retinal degeneration (4 papers, 2016 to 2022). Degeneration of the retina. "With the emerging role of enzymes involved in tubulin glycylation and glutamylation in retinal degeneration, the clinical and cellular phenotype associated with PRPF6 and PRPF31 mutations, TTLL3 is an extremely interesting candidate for further investigation." (PMID 36176300, 2022). "For example, why variants in the U5 snRNP genes PRPF6, PRPF8 and SNRNP200 are associated with retinal degeneration in adRP, while variants in the U5 snRNP genes EFTUD2 and TXNL4A are linked to craniofacial disorders, is not understood." (PMID 31304552, 2019). "Furthermore, the mutation of ubiquitously expressed and highly conserved splicing factors PRPF6, PRPF8, and PRPF31 causes retinal degeneration, suggesting a specialized role of the splicing machinery in the retina." (PMID 27151457, 2016). "In this study UV exposure is used as a research tool to investigate the effect of DNA damage on PRPF6 and PRPF31 mutant cells, but oxidative stress, from the high level of reactive oxygen species in the RPE cells, plays more of a role in retinal degeneration in vivo." (PMID 36176300, 2022).
hepatocellular carcinoma (3 papers, 2020 to 2025). A malignant tumor that arises from hepatocytes. "PRPF6 is closely related to the advanced stage of hepatocellular cancer, which is consistent with our findings." (PMID 37303939, 2021). "PRPF6 activates AR/AR-Vs to promote the progression of hepatocellular cancer and prostate cancer." (PMID 37303939, 2021).
lymphoma (2 papers, 2009 to 2013). A malignant (clonal) proliferation of B- lymphocytes or T- lymphocytes which involves the lymph nodes, bone marrow and/or extranodal sites. "PRPF6 is excessively expressed in the lymph node of lymphoma and is believed to be a probable target for tumor metastasis studies." (PMID 23874428, 2013).
colon adenocarcinoma (1 paper, 2022). "(B) DNA–RNA and RNA–protein correlations for representative complex and non-complex genes frequently gained (FAM210B and PRPF6) or lost (CTDNEP1 and INPP5K) in colon adenocarcinoma (COAD)." (PMID 36129397, 2022).
COVID-19 (1 paper, 2022). A disease caused by infection with severe acute respiratory syndrome coronavirus 2. "Our results showed that six spliceosomal component proteins (DDX5, DDX17, DDX39B, PRPF6, SNRNP40, and SNRNP200) were significantly down-regulated in COVID-19 patients." (PMID 35421082, 2022). "Furthermore, we observed that the major transcript of multiple genes switched to a different transcript (isoform switching) between COVID-19 patients and controls, such as IL2, IL34, SERPINE2, NCBP1, HRAS, PRPF6, NCBP2, and LUC7L2." (PMID 35421082, 2022).
Kufs disease (1 paper, 2021). "Furthermore, another missense variant, c.1430A > G, p.Asn477Ser, was identified within PRPF6 co-segregating with the neurodegenerative Kufs disease." (PMID 33584830, 2021). "However, further work is required to confirm whether this PRPF6 p.Asn477Ser variant has a role in either Kufs disease or the visual impairment (Ru°žičková and Staněk, 2017)." (PMID 33584830, 2021).
lymph node metastasis (1 paper, 2021). "The results showed that PRPF6 was closely related to advanced FIGO stages but was not related to patient age, differentiation, or lymph node metastasis." (PMID 37303939, 2021).
prostate carcinoma (1 paper, 2021). A carcinoma that arises from epithelial cells of the prostate gland. "We then wonder to test the association between PRPF6 and AR in prostate cancer cells." (PMID 33390843, 2021). "To investigate the physiological role of PRFP6 in prostate cancer, we examined the endogenous protein expressions of PRPF6 in four cultured prostate cancer-derived cell lines as indicated." (PMID 33390843, 2021). "Taken together, these data suggested that PRPF6 promotes prostate cancer cell growth under androgen-depleted condition in vitro and in vivo." (PMID 33390843, 2021). "Having revealed the involvement of PRPF6 in AR signaling and growth of prostate cancer cells, we next examined the expression of PRPF6 in clinical prostate cancer samples." (PMID 33390843, 2021). "As we previously reported that PRPF6 enhances transactivation function of AR 25, we then analyzed the impact of PRPF6 on the growth and motility characteristics of AR-positive prostate cancer cells by lentivirus-mediated knockdown of PRPF6." (PMID 33390843, 2021). "In three AR-positive prostate cancer cell lines, PRPF6 was lowly expressed in LNCaP cells that expressed AR-FL but not AR-Vs." (PMID 33390843, 2021). "Taken together, our results demonstrate that PRPF6 is involved in enhancement of oncogenic AR signaling, which provides an insight to potential therapeutic strategies for prostate cancer, especially for CRPC." (PMID 33390843, 2021). "Our data demonstrated that PRPF6 plays a vital role in modulation of oncogenic AR signaling pathway and promotes the progression of prostate cancer and CRPC." (PMID 33390843, 2021). "Here, our results have demonstrated PRPF6 acts as a key regulator for action of both AR-FL and AR-V7, thereby participating in the enhancement of AR-FL and AR-V7-induced transactivation in prostate cancer." (PMID 33390843, 2021). "Moreover, results of immunofluorescence experiments showed that endogenous PRPF6 located in the nucleus in prostate cancer cells including LNCaP, CWR22Rv1, and DU145." (PMID 33390843, 2021). "Moreover, PRPF6 depletion reduces tumor growth in prostate cancer-derived cell lines and results in significant suppression of xenograft tumors even under castration condition in mouse model." (PMID 33390843, 2021). "We then set up to test whether PRPF6 is necessary for prostate cancer cell growth under androgen-depleted condition." (PMID 33390843, 2021). "Our data support a previously unknown role of PRPF6 during prostate cancer progression, which may provide an insight to potential therapeutic strategies for prostate cancer, especially for CRPC." (PMID 33390843, 2021). "Besides a cofactor of AR-FL, our data showed PRPF6 also co-activates AR-V7 mediated transcription, indicating that PRPF6 plays an important role in enhancing AR-FL and AR-V7 action in prostate cancer and CRPC." (PMID 33390843, 2021). "However, little work has been done to understand the molecular mechanism underlying the modulation function of PRPF6 on AR action and the role of PRPF6 in prostate cancer." (PMID 33390843, 2021). "Collectively, our results suggest PRPF6 is involved in enhancement of oncogenic AR signaling, which support a previously unknown role of PRPF6 during progression of prostate cancer and castration-resistant prostate cancers." (PMID 33390843, 2021). "Furthermore, PRPF6 is obviously highly expressed in human prostate cancer samples." (PMID 33390843, 2021). "Here, we provided the evidence to show that pre-mRNA processing factor 6 (PRPF6) acts as a key regulator for action of both AR full length (AR-FL) and AR variant 7 (AR-V7), thereby participating in the enhancement of AR-FL and AR-V7-induced transactivation in prostate cancer." (PMID 33390843, 2021). "The stain intensity of PRPF6 was increased in prostate cancer tissues compared with the matched adjacent noncancerous tissues." (PMID 33390843, 2021).
prostate carcinoma (continued). "We then examined the expression of PRPF6 in 71 pairs of prostate cancer tissues and the matched adjacent noncancerous tissues by immunohistochemical stain (IHC)." (PMID 33390843, 2021).
Usher syndrome (1 paper, 2023). A syndromic diseae characterized by the association of sensorineural deafness (usually congenital) with retinitis pigmentosa and progressive vision loss. "During this process, SANS interacts with the U4/U6 and U5 snRNP-specific proteins PRPF31 and PRPF6 and regulates splicing, which is disturbed by variants of USH1G/SANS causative for human Usher syndrome (USH), the most common form of hereditary deaf–blindness." (PMID 38139438, 2023).
cancer (14 papers, 2010 to 2024). A tumor composed of atypical neoplastic, often pleomorphic cells that invade other tissues. "Additionally, PRPF6, an integral component of the tri-snRNP (small ribonucleoprotein) spliceosome complex, propels cancer proliferation through its involvement in the preferential splicing of genes associated with cellular proliferation." (PMID 38280969, 2024). "Knockdown of PRPF6 expression in human cancer cell lines with increased levels of PRPF6 inhibited cell growth in vitro, and inducible knockdown of PRPF6 in xenograft tumours led to tumour shrinkage only in tumour models with high PRPF6 expression." (PMID 33584830, 2021). "Furthermore, recurrent somatic mutations or changes in the expression levels of a number of U5 snRNP proteins (PRPF6, PRPF8, EFTUD2, DDX23, and SNRNP40) have been associated with human cancers." (PMID 33584830, 2021). "PRPF6, as a splicing protein, acts as an oncogene in many cancers." (PMID 37303939, 2021). "However, somatic mutations in PRPF8 have now been linked to myeloid neoplasms, while altered expression levels of several other U5 snRNP proteins (PRPF6, EFTUD2, SNRNP40, and DDX23) have been associated with human cancer." (PMID 33584830, 2021). "Of the eight modeling RBPs, half were upregulated including PABPC1, PRPF6, OAS1, IPO7, and half were downregulated including RBM5, RBM6, LSM12, and FXR7 in cancer cases." (PMID 33584809, 2020). "As documented, the increased PRPF6 can alter the constitutive and alternative splicing of ZAK kinase, thereby activating cancer-related pathways, like AP-1, ERK, and JNK." (PMID 32195181, 2020). "However, no role in cancer of PRPF6 or other related genes is known." (PMID 20126641, 2010).
tumor (7 papers, 2013 to 2024). "Previous studies have reported that ADRM1 is upregulated and promotes cell growth in CRC, while there have been few studies on the role of PRPF6 in tumour proliferation." (PMID 36551532, 2022). "Compared with control cells, PRPF6-knockdown cells showed slower growth rate, smaller volume and decreased tumor weight." (PMID 33390843, 2021). "Results showed that PRPF6 knockdown reduced tumor burden, with smaller volumes and slower growth rate of the xenograft tumors." (PMID 33390843, 2021). "To further validate the role of PRPF6 in tumor growth under castration conditions, we next performed in vivo xenograft assays in castrated male mice." (PMID 33390843, 2021). "Tumor formation from castration-resistant CWR22Rv1 cells was observed in castrated male mice, and knockdown of PRPF6 significantly suppressed xenograft tumor growth derived from CWR22Rv1 cells." (PMID 33390843, 2021). "In line with the tumor growth curve, the tumor weights of cells with PRPF6 knockdown were significantly lower." (PMID 33390843, 2021). "The study concerning the function of PRPF6 in tumor is rarely reported." (PMID 33390843, 2021). "The results showed that knockdown of PRPF6 inhibited tumor expansion and weight." (PMID 37303939, 2021). "Among these genes, PKM, CAV1, GLI3, PICK1, PRPF6, and UBE3A have been identified as oncogenes, and play a pivotal role in orchestrating tumor-host interactions, fostering tumor growth, promoting metastasis, enhancing resistance to therapy, and ensuring cellular survival." (PMID 38280969, 2024).
PRPF6 also shares sentences with these, for which no sentence is quoted: neurodegenerative disease (2 papers); paranoid schizophrenia (2); psychosis (2); acrofacial dysostosis (1); bacterial infection (1); Burn-McKeown syndrome (1); cardiac conduction disease (1); cardiovascular diseases (1); cerebrocostomandibular syndrome (1); cervical cancer (1); cognitive decline (1); cone dystrophy (1); cone-rod dystrophy (1); dementia with (1); endometrial cancer (1); infection (1); mitochondrial genetic disorders (1); Nager syndrome (1); nervous system disorder (1); optic atrophy (1); ovarian carcinoma (1); specific language impairment (1).